GPR135 (G protein-coupled receptor 135)
Description:
Orphan receptor. Has spontaneous activity for beta-arrestin recruitment. Shows a reciprocal regulatory interaction with the melatonin receptor MTNR1B most likely through receptor heteromerization.
Synonyms: HUMNPIIY20; PAFR
Tractability: Small molecule: it belongs to a druggable protein family. Antibody: UniProt places it where antibodies can reach, with high confidence; its Gene Ontology location is reachable by antibodies, with high confidence; UniProt predicts a signal peptide or a membrane-spanning region. PROTAC: ubiquitination databases record sites on it.
Target class: Family A G protein-coupled receptor; Membrane receptor
Gene: Protein-coding gene on chromosome 14 (59,429,022 to 59,465,380, reverse strand). Ensembl gene ENSG00000181619.
Subcellular location: Cell membrane; Endosome membrane
Gene Ontology:
Molecular function: arrestin family protein binding; protein binding; G protein-coupled receptor activity
Biological process: G protein-coupled receptor signaling pathway
Cellular component: endosome; endosome membrane; plasma membrane; membrane
Genetic constraint (gnomAD): Loss-of-function variants: 24 observed, 14.76 expected, observed/expected ratio (o/e) 1.63, 90% interval 1.15 to 1.94. The synonymous counts are far from expectation, so gnomAD's model fits this gene poorly and the ratio says little. Missense variants: 776 observed, 631.54 expected, observed/expected ratio (o/e) 1.23, 90% interval 1.16 to 1.3. Synonymous variants: 368 observed, 298.61 expected, observed/expected ratio (o/e) 1.23, 90% interval 1.13 to 1.34.
Homologues: Orthologues: chimpanzee GPR135 (99% identical), pig GPR135 (81% identical), rat Gpr135 (78% identical), mouse Gpr135 (77% identical), dog GPR135 (76% identical), rabbit GPR135 (68% identical), tropical clawed frog gpr135 (52% identical), zebrafish gpr135 (48% identical). Paralogues in human: GPR61 (18% identical), GPR176 (18% identical), GPR62 (16% identical).
Diseases named in the same sentence as GPR135 in open-access papers:
GPR135 is named in the same sentence as 4 diseases in open-access papers, as found by Europe PMC text mining. Sharing a sentence is not in itself a finding about the gene and the disease. The quoted sentences say what the papers report.
Azoospermia (1 paper, 2023). Absence of any measurable level of sperm,whereby spermatozoa cannot be observed even after centrifugation of the semen pellet. "Our findings indicate that GPR135 has high diagnostic accuracy in azoospermia samples and a positive correlation with the length of hospital-free days in COVID-19 patients." (PMID 37283758, 2023). "Of these, GPR135 exhibited the highest diagnostic performance in azoospermia samples (AUC = 0.972)." (PMID 37283758, 2023). "The expression levels of GPR135 in azoospermia tissues positively correlated with the levels of “DYNLL2” and “EPB41L3” and negatively correlated with GLO1 expression." (PMID 37283758, 2023). "In this study, we identified four genes, GLO1, GPR135, DYNLL2, and EPB41L3 that were strongly associated with azoospermia and COVID-19." (PMID 37283758, 2023). "GPR135, a GPCR, has received limited research attention, and its involvement in azoospermia and COVID-19 remains unclear." (PMID 37283758, 2023).
ovarian carcinoma (1 paper, 2016). A malignant neoplasm originating from the surface ovarian epithelium. "The GPR135 gene is a target for hypermethylation in ovarian cancer genesis." (PMID 27572937, 2016).
tumor (1 paper, 2023). "Previous studies have shown that GPR135 activators can suppress tumor activation and are associated with affective disorders." (PMID 37283758, 2023).
GPR135 also shares sentences with these, for which no sentence is quoted: COVID-19 (1 paper).